SLC30A2 (solute carrier family 30 member 2)
Description:
[Isoform 1]: Electroneutral proton-coupled antiporter concentrating zinc ions into a variety of intracellular organelles including endosomes, zymogen granules and mitochondria. Thereby, plays a crucial role in cellular zinc homeostasis to confer upon cells protection against its potential cytotoxicity. Regulates the zinc concentration of milk, through the transport of zinc ions into secretory vesicles of mammary cells. By concentrating zinc ions into lysosomes participates to lysosomal-mediated cell death during early mammary gland involution. [Isoform 2]: Electroneutral proton-coupled antiporter mediating the efflux of zinc ions through the plasma membrane.
Synonyms: ZnT-2; ZNT2; PP12488; TNZD
Tractability: Antibody: UniProt places it where antibodies can reach, with high confidence; its Gene Ontology location is reachable by antibodies, with high confidence; UniProt predicts a signal peptide or a membrane-spanning region. PROTAC: ubiquitination databases record sites on it.
Gene: Protein-coding gene on chromosome 1 (26,037,252 to 26,046,136, reverse strand). Ensembl gene ENSG00000158014.
Subcellular location: Cytoplasmic vesicle, secretory vesicle membrane (Isoform 1); Zymogen granule membrane; Endosome membrane; Lysosome membrane; Mitochondrion inner membrane; Cell membrane (Isoform 2)
Subcellular location (Human Protein Atlas): Vesicles
Pathways (Reactome):
Transport of small molecules: Zinc efflux and compartmentalization by the SLC30 family
Gene Ontology:
Molecular function: identical protein binding; protein binding; zinc ion transmembrane transporter activity; zinc:proton antiporter activity; monoatomic cation transmembrane transporter activity
Biological process: zinc ion import into lysosome; zinc ion import into organelle; intracellular zinc ion homeostasis; response to zinc ion; zinc ion import into mitochondrion; zinc ion import into zymogen granule; zinc ion transmembrane transport; intercellular transport; monoatomic cation transport; transmembrane transport
Cellular component: cytoplasm; cytoplasmic vesicle membrane; endosome membrane; late endosome; lysosomal membrane; mitochondrial inner membrane; plasma membrane; transmembrane transporter complex; zymogen granule membrane; cytoplasmic vesicle; membrane; transport vesicle membrane; vesicle membrane
Genetic constraint (gnomAD): Loss-of-function variants: 18 observed, 38.21 expected, observed/expected ratio (o/e) 0.47, 90% interval 0.32 to 0.7. The upper end of that interval is the gene's LOEUF score, 0.7, which puts it in group 2 of 6, group 1 being the genes least tolerant of losing a copy. Missense variants: 358 observed, 459.11 expected, observed/expected ratio (o/e) 0.78, 90% interval 0.71 to 0.85. Synonymous variants: 181 observed, 185.36 expected, observed/expected ratio (o/e) 0.98, 90% interval 0.86 to 1.11.
Gene-disease validity (ClinGen):
ClinGen rates the evidence that SLC30A2 causes each of these diseases.
zinc deficiency, transient neonatal (autosomal dominant): Definitive.
Homologues: Orthologues: chimpanzee SLC30A2 (99% identical), macaque SLC30A2 (97% identical), rabbit SLC30A2 (86% identical), guinea pig SLC30A2 (84% identical), mouse Slc30a2 (79% identical), pig SLC30A2 (79% identical), rat Slc30a2 (79% identical), tropical clawed frog slc30a2 (70% identical), zebrafish slc30a2 (58% identical), dog SLC30A2 (54% identical). Paralogues in human: SLC30A3 (50% identical), SLC30A8 (47% identical), SLC30A4 (39% identical), SLC30A1 (25% identical), SLC30A10 (21% identical), SLC30A5 (21% identical), SLC30A6 (18% identical), SLC30A7 (16% identical).
Diseases named in the same sentence as SLC30A2 in open-access papers:
SLC30A2 is named in the same sentence as 22 diseases in open-access papers, as found by Europe PMC text mining. Sharing a sentence is not in itself a finding about the gene and the disease. The quoted sentences say what the papers report.
Zinc deficiency (17 papers, 2013 to 2025). A deficiency of the essential metal Zinc; an essential cofactor for many enzymes. "For instance, genetic variants of SLC30A2 have been associated with zinc deficiency, which affects brain development and produces neurobehavioral impairments." (PMID 37486945, 2023). "Loss of function (LoF) mutations in the zinc transporter SLC30A2/ZnT2 result in impaired zinc secretion into breast milk consequently causing transient neonatal zinc deficiency (TNZD) in exclusively breastfed infants." (PMID 30450693, 2019). "Most probably, an association of both heterozygosity for SLC30A2 gene mutation and dietary zinc deficiency in the mothers was contributing to the clinical manifestations in the infants." (PMID 25548552, 2014). "We report two novel missense mutations in the SLC30A2/ZnT2 gene causing W152R and S296L substitutions in a mother who produced zinc-deficient breast milk (>90% reduction), resulting in severe zinc deficiency in her breast-fed infant." (PMID 23741301, 2013). "In this study we identified two novel missense mutations in the SLC30A2/ZnT2 gene in a Japanese mother who secreted zinc-deficient breast milk, causing her breast-fed infant to develop severe zinc deficiency that was reversed by zinc replacement therapy." (PMID 23741301, 2013). "If women harboring loss of function (LoF) mutations in SLC30A2/ZnT2 also suffered from low milk supply, supplementary foods must be provided to the infant relatively early (i.e., baby formula) which will therefore mask the zinc deficiency in the milk." (PMID 32455695, 2020). "Since this pioneering report, at least 10 distinct mutations in SLC30A2/ZnT2 were identified in mothers producing zinc-deficient milk, and consequently in the blood of their exclusively breastfed infants, which developed severe zinc deficiency." (PMID 32455695, 2020). "We could not rule out whether mother and child presented heterozygosity for a SLC39A4 or SLC30A2 gene mutation or whether the clinical features could be due to a dietary zinc deficiency of the mothers and/or increased zinc requirements of the infants." (PMID 25548552, 2014). "Knockout mice for ZnT2 exhibited irregular anatomy and function of the mammary gland, and several mutants have been identified in humans ZnT2 (SlC30A2), which has impaired zinc secretion into breast milk and promotes transient neonatal zinc deficiency in breastfed infants." (PMID 38999774, 2024). "Heterozygous mutations in the SLC30A2/ZnT2 gene are associated with transient neonatal zinc deficiency (TNZD), characterized by an insufficient secretion of zinc into human milk causing zinc deficiency in breastfed infants." (PMID 41325371, 2025). "In 2006, the first mutation in the SLC30A2/ZnT2 gene was found to be associated with transient neonatal zinc deficiency (TNZD), a disorder that leads to severe zinc deficiency exclusively in breastfed infants." (PMID 32455695, 2020). "Mice experiments showed that dietary zinc deficiency decreased urinary but not plasma zinc levels, and upregulated kidney Slc30a2 expression." (PMID 41325371, 2025).
breast carcinoma (8 papers, 2016 to 2021). "SLC30A2 is dysregulated in breast cancer lines and SLC30A2-mediated Zn accumulation in mitochondria is associated with increased mitochondrial oxidation." (PMID 33110097, 2020).
breast tumor (4 papers, 2012 to 2024). "SLC30A2-overexpression represses the cytotoxic effects of zinc hyper-accumulation in malignant metallothionein-null T47D breast tumor cells." (PMID 33110097, 2020).
transient neonatal zinc deficiency (3 papers, 2018 to 2020). "In addition, mutations in ZNT2/SLC30A2 result in transient neonatal zinc deficiency (TNZD) in breastfeeding infants of affected mothers, whereas ZNT10/SLC30A10 mutations cause Parkinsonism and dystonia with hypermagnesemia, polycythaemia, and hepatic cirrhosis." (PMID 30237557, 2018). "In the past decade, the human zinc transporter 2 (ZnT2/SLC30A2) was found to be the predominant transporter mediating the translocation of zinc into breast milk in lactating mammary epithelial cells, involved in clinical cases of transient neonatal zinc deficiency (TNZD)." (PMID 30388104, 2018).
cervical cancer (1 paper, 2022). A primary or metastatic malignant neoplasm involving the cervix. "Data in the UALCAN tool revealed that mRNA expressions of SLC30A1, SLC30A7 and SLC30A10 were significantly higher in cervical cancer tissues, while SLC30A2 and SLC30A8 mRNA levels were decreased compared to normal tissues." (PMID 35154468, 2022). "For tumor stages, SLC30A1, SLC30A7 and SLC30A10 groups significantly varied, whereas SLC30A2, SLC30A3, SLC30A4, SLC30A5, SLC30A6, SLC30A8 and SLC30A9 did not significantly differ in cervical carcinoma." (PMID 35154468, 2022).
colon adenocarcinoma (1 paper, 2010). "Slc30a2, the second most up-regulated gene in our set of colon adenocarcinomas, codes for the protein Znt2 which has been reported to promote zinc efflux into intracellular vesicles when Zn concentration rises in the cell." (PMID 20459814, 2010).
colon cancers (1 paper, 2022). "GGH, CACNG4, MME, SLC30A2, CKMT2, SYN3, and SLC22A31 were identified as differentially expressed both in glycolytic-cholesterogenic subgroups as well as between colon cancers and healthy samples, and were involved in glycolysis‒cholesterol synthesis." (PMID 36569910, 2022).
tumor (3 papers, 2010 to 2022). "These were Defcr4, S100A9, Igfbp5, Slc30a2 and Lgr5 (leucine-rich repeat containing G protein coupled receptor 5) which were up-regulated and Mptx, Slc26a3, Retnla, Muc2 and Hpgd (hydroxyprostaglandin dehydrogenase 15) which were down-regulated in tumours." (PMID 20459814, 2010).
SLC30A2 also shares sentences with these, for which no sentence is quoted: infection (3 papers); breast disease (2); cancer (2); prostate carcinoma (2); bacterial infection (1); Dystonia (1); dystonia 1 (1); infectious colitis (1); inflammation (1); intestinal disease (1); intestinal infections (1); nutritional deficiency (1); Parkinsonism (1); respiratory disease (1).